PRMT5 (protein arginine methyltransferase 5)
Diseases named in the same sentence as PRMT5 in open-access papers (continued):
Sharing a sentence is not in itself a finding about the gene and the disease.
cervical carcinoma (continued). "Notably, a significant correlation was found between elevated PRMT5 expression and poor survival outcomes in cervical cancer patients, underscoring its potential role in promoting tumorigenesis." (PMID 41463372, 2025). "Therefore, we investigated the impact of PRMT5 expression on migration and apoptosis in a cervical cancer cell line." (PMID 41463372, 2025). "Thus, our study provides compelling evidence supporting the potential targeting of PRMT5 as a viable immunotherapeutic strategy for cervical cancer." (PMID 41463372, 2025). "In addition, elevated PRMT5 expression in cervical cancer promotes the epithelial–mesenchymal transition (EMT) process, and prior studies have also reported overexpression of other PRMT family members in various cancers." (PMID 41463372, 2025). "Taken together, these findings revealed that PRMT5 expression was associated with the migration, invasion and apoptosis of cervical cancer cells, while having no significant impact on their proliferation." (PMID 41463372, 2025). "Collectively, these findings identify CXCL10 as a key chemokine upregulated upon PRMT5 deficiency, suggesting that PRMT5 may influence the recruitment of CD8+ T cells via the CXCL10 signaling pathway in cervical cancer." (PMID 41463372, 2025). "The elevated expression of PRMT5 suggests that PRMT5 may be a possible biomarker for numerous cancers, including cervical cancer." (PMID 36144454, 2022). "More importantly, EPZ015666 promotes the conversion of 5mC to 5hmC in cervical cancer cells, which may depend on the inhibitory effect of PRMT5 on TET1 expression." (PMID 33953349, 2021). "To further explore whether PRMT5 could be an effective target for the treatment of cervical cancer, we selected EPZ015666, a specific inhibitor of PRMT5, to assess a possible therapeutic effect." (PMID 34522232, 2021). "Collectively, these findings suggested that STAT1 expression affected by PRMT5-mediated epigenetic regulation could drive PD-L1 expression, which promoted the development of cervical cancer." (PMID 34522232, 2021). "Additionally, PRMT5 promotes the invasion and metastasis of cervical cancer in vitro and in vivo and its expression is markedly upregulated in multiple human cancers." (PMID 33953349, 2021). "However, the molecular mechanism and function of PRMT5 in the metastasis of cervical cancer requires further analysis." (PMID 33953349, 2021). "The biological function of PRMT5 remains poorly understood in cervical cancer metastasis." (PMID 33953349, 2021). "However, this study at least provides a theoretical basis for the use of PRMT5 inhibitors in the treatment of cervical cancer." (PMID 34522232, 2021). "We next investigated the role of PRMT5 in the metastasis of cervical cancer." (PMID 33953349, 2021). "To investigate the potential oncogenic role of PRMT5 and whether it could be a target for treating cervical cancer, we initially assessed the PRMT5 protein levels in one normal human cervical cell line and four human cervical cancer cell lines." (PMID 34522232, 2021). "Moreover, upon TCGA database, cervical cancer patients with high PRMT5 expression were found to have a significantly worse overall survival (OS), progression free interval (PFI) and disease free interval (DFI)." (PMID 34522232, 2021). "In this study, we firstly uncovered that PRMT5 knockdown in cervical cancer cells decreased PD-L1 expression by regulating the transcription of STAT1 gene through symmetric dimethylation of histone H3R2, and increased the number and function of T cells in the tumor microenvironment." (PMID 34522232, 2021). "In addition, a STAT1 inhibitor (Fludarabine) blocked IFN-γ-induced PD-L1 expression in cervical cancer cells, further confirming that PRMT5 regulated PD-L1 expression through STAT1." (PMID 34522232, 2021).
cervical carcinoma (continued). "Importantly, we found that the elevated expression of PRMT5 was significantly correlated poor survival outcome of cervical cancer patients, and the PRMT5 inhibitor therapy was effective in a tumor-bearing mouse model of cervical cancer." (PMID 34522232, 2021). "We found that expression of PRMT5 was upregulated in cervical cancer and multiple carcinomas." (PMID 33953349, 2021). "Furthermore, we identified that PRMT5 represses the expression of CXCL10 in cervical cancer cells." (PMID 41463372, 2025). "However, since PRMT5 is upregulated in cervical cancer, this could suggest overexpression of circ-PRMT5, which possibly drives cervical cancer progression by sponging miRNAs such as miR-145." (PMID 36144454, 2022). "Whether PRMT5 inhibitors are effective in cervical cancer patients requires further investigation." (PMID 34522232, 2021). "Furthermore, the PRMT5 inhibitor EPZ015666 treatment could suppress tumor growth in a cervical cancer transplanted tumor model." (PMID 34522232, 2021). "To evaluate the role of PRMT5 in cervical cancer development, we constructed tumor models utilizing C57BL/6 mice and CD8 KO mice, which included both control cells and U14 cells with PRMT5 knockdown." (PMID 41463372, 2025). "PRMT5, WD45 and RIOK1 are expressed in different cancer cell lines such as cervical cancer HeLa-CD95 and B lymphoblastoid SKW 6.4 cells." (PMID 38730267, 2024). "Thus, our study highlights that PRMT5 may be a potential target for cervical cancer therapy." (PMID 34522232, 2021). "To study the effect of PRMT5 in tumorigenesis of cervical cancer, we established tumor models in C57BL/6 mice with control cells and PRMT5 knockdown U14 cells." (PMID 34522232, 2021). "Mechanistically, PRMT5 enhanced the transcription of STAT1 through symmetric dimethylation of histone H3R2 and thus promoted PD-L1 expression in cervical cancer cells." (PMID 34522232, 2021). "Our data suggest that the PRMT5 inhibitor EPZ015666 can lead to an induction of TET1 expression and 5hmC, and inhibit the invasive potential of cervical cancer cells, making PRMT5 a potential target for cancer diagnosis and treatment." (PMID 33953349, 2021). "Further analysis indicated that overexpression of PRMT5 promotes EMT and the invasive potential of cervical cancer cells." (PMID 33953349, 2021). "The PRMT5 inhibitor EPZ015666 suppressed EMT and the invasive potential of cervical cancer cells, and led to an induction of TET1 expression and 5hmC." (PMID 33953349, 2021). "Our results clarified a new mechanism which PRMT5 knockdown in cervical cancer cells drives an antitumor function via reprogramming T cell-mediated response and regulating PD-L1 expression, and indicated PRMT5 inhibitor could be a potential therapeutic strategy in cervical cancer." (PMID 34522232, 2021). "This study demonstrates that the Snail/PRMT5/NuRD(MTA1) complex promotes the invasion and metastasis of cervical cancer in vitro and in vivo." (PMID 33953349, 2021). "However, the precise mechanism by which PRMT5 mediated the tumor immune microenvironment, particularly CD8+ T cell recruitment in cervical cancer remains elusive." (PMID 41463372, 2025). "PRMT5 binds to the transcription factors Snail and NuRD complexes to form transcriptional inhibitory complexes, regulating TET1 and E‐cadherin methylation and deacetylation to promote invasion and metastasis of cervical cancer." (PMID 39823268, 2025). "Significant inhibition of tumor growth was observed in cervical cancer using a mouse model lacking PRMT5." (PMID 41463372, 2025). "In cervical cancer, PRMT5 (protein arginine N-methyltransferase 5) forms a complex with Snail, HDAC1/2, MTA1, Mep50, and NuRD, and represses the expression of TET1 and E-cadherin by histone methylation on their promoter regions, leading to EMT initiation and increased risk of metastasis." (PMID 37369946, 2023).
cervical carcinoma (continued). "Moreover, similar to Snail1 in cervical cancer, ZEB2 also binds to PRMT5 and the NuRD complex to form a multimeric transcriptionally repressive unit." (PMID 35884488, 2022). "We also noticed STAT1 blocking reagent Fludarabine could prevent PD-L1 expression of cervical cancer cells induced by IFN-γ, thus proving PRMT5 did regulate PD-L1 expression depending on STAT1." (PMID 34522232, 2021). "In cervical cancer cells, TSA (1 μM) induces autophagy by significantly suppressing protein arginine methyltransferase 5 (PRMT5) and transient receptor potential cation channel, subfamily V, member 6 (TRPV6) levels and enhancing stanniocalcin 1 (STC1) and JNK levels." (PMID 34575981, 2021). "The absence of PRMT5 significantly inhibited tumor growth in a cervical cancer transplanted tumor model, and importantly, PRMT5 absence in tumors led to increase the number and enhance the function of tumor infiltrating T cells." (PMID 34522232, 2021). "This demonstrated that PRMT5 knockdown induced an antitumor response through regulation of CXCL10 expression and suggested that PRMT5 inhibitors could serve as a promising therapeutic strategy for cervical cancer treatment." (PMID 41463372, 2025). "Likewise, we found that PRMT5 expression did not affect the proliferation of a cervical cancer cell line in vitro." (PMID 34522232, 2021). "In this study, we discovered that PRMT5 deletion in tumor cells inhibited the tumor growth in a cervical cancer model of C57BL/6 mice, not in a model of nude mice, clearly implying that the immune cells in the tumor microenvironment indeed played an important role." (PMID 34522232, 2021). "Our previous research found that knockdown of PRMT5 could increase the number and function of CD8+ T cells, and it has been confirmed that the absence of PRMT5 reprograms the T cell-mediated response by regulating the expression of PD-L1, promoting the anti-tumor immune response in cervical cancer." (PMID 41463372, 2025). "In the current study, we focused on elucidating the novel mechanism of the PRMT5/CXCL10 axis in vivo, primarily utilizing mouse models and lacking a direct relevance to human cervical cancer." (PMID 41463372, 2025).
acute myeloid leukemia (17 papers, 2020 to 2026). Acute myeloid leukemia (AML) is a group of neoplasms arising from precursor cells committed to the myeloid cell-line differentiation. "Conversely, PRMT5-catalyzed SDMA of SRSF1 was shown to control cassette-exon choice in acute myeloid leukemia, underscoring the conserved role of SRSF1 methylation across cancers." (PMID 40846633, 2025). "Profiling the PRMT5 methylome identified 11 proteins that are essential in the proliferation of acute myeloid leukaemia (AML) cells." (PMID 37795443, 2023). "GSK3326595, a potent and selective PRMT5 inhibitor with demonstrated efficacy in multiple tumor models, was recently investigated in a phase II clinical study in human subjects with acute myeloid leukemia." (PMID 35884488, 2022). "PRMT5 activity possesses myeloproliferative effects that stem from its interaction with receptor tyrosine kinase FLT3, a protein often mutated in acute myeloid leukemia (AML)." (PMID 33440687, 2021). "Interestingly, in acute myeloid leukemia (AML), loss of PRMT5 leads to a global increase in H3K27me3 levels." (PMID 41204384, 2025). "As a potential molecular target, the PRMT5 inhibitor (GSK3326595) is currently in phase I/II clinical trials for acute myeloid leukemia (AML) and other cancer types." (PMID 38666828, 2024). "Moreover, in AML (adult acute myeloid leukemia) cells, 50% of the genes downregulated by PRMT5 inhibition were partially rescued in expression upon inhibition of EZH2 activity, providing evidence of the critical role for PRC2-EZH2 in methylation and subsequent repression of these target genes." (PMID 33804165, 2021). "Similarly, in acute myeloid leukaemia (AML) cell lines, combination PRMT1 and PRMT5 inhibition also result in synergistic increases in novel ASEs." (PMID 34680285, 2021).
colon carcinoma (15 papers, 2017 to 2024). "In many human cancers such as liver, breast, cervix, prostate, lung, and colon cancer, PRMT5 is highly expressed and associated with their poor prognosis." (PMID 32759981, 2020). "Further, this combined therapy has significant potential to be effective in colon cancers as well as in cancers at other sites that are sensitive to PRMT5-mediated tumorigenesis." (PMID 38000655, 2024). "PRMT5-mediated YBX1-R205 methylation was also shown to affect NFkB-dependent gene expression promoting colon cancer cell proliferation and anchorage-independent growth." (PMID 36658119, 2023). "Cells from an MTAP-deleted colon carcinoma cell line displayed reduced PRMT5 methylation activity and increased sensitivity to PRMT5 depletion." (PMID 34573422, 2021). "PRMT5 has previously been shown to be overexpressed in multiple human cancers, including prostate, lung, and colon cancers, yet its role in OS is under investigation." (PMID 32023548, 2020). "Previously, the expression of specific isoforms of PRMT1 variants were shown to be significantly associated with nodal status, TNM stage, and tumor grade, and both PRMT4 and PRMT5 are highly expressed in colon cancer." (PMID 29507670, 2018). "Thus, overall these findings suggest that NAA40 facilitates survival of colon cancer cells partly through upregulation of PRMT5 expression." (PMID 30858358, 2019). "In addition to transcriptional activation of FGFR genes by PRMT5 in lung and colon cancers, direct arginine methylation by PRMT5 regulates activity of several proteins functioning in growth factor signaling pathways crucial to the proliferation, differentiation and survival of cancer cells." (PMID 32743345, 2020). "SIRT7 also deacetylates WD repeat domain 77 (WDR77) and thereby disrupts the interaction between WDR77 and protein arginine methyltransferase 5 (PRMT5), protecting against proliferation and migration of colon cancer cells." (PMID 37676263, 2024).
multiple myeloma (15 papers, 2018 to 2025). "In multiple myeloma (MM) patients, PRMT5 is often overexpressed and is associated with decreased progression-free survival and overall survival." (PMID 36358861, 2022). "However, the biological functions of PRMT5 in multiple myeloma (MM) and the underlying molecular mechanisms remain unclear." (PMID 34531375, 2021). "GSK591, an inhibitor of protein arginine methyltransferase 5 (PRMT5), lowers H4R3me2s levels at the caspase-1 promoter, thereby elevating caspase-1 expression and inducing pyroptosis in multiple myeloma cells." (PMID 40555741, 2025). "Druggability was assessed in OPM2, JJN3, AMO1 and XG7 human myeloma cell lines using the PRMT5-inhibitor EPZ015938." (PMID 35757005, 2022). "In this study, in addition to our cohort, we extracted clinical and RNA sequencing data from the Multiple Myeloma Research Foundation (MMRF) CoMMpass study to assess the clinical significance of PRMT5." (PMID 34531375, 2021). "It has been reported that PRMT5 regulates pyroptosis via inhibiting the CASP1 in myeloma cells." (PMID 37600810, 2023). "Consistent with this, a recent study also presented evidence that PRMT5 may functionally interact with TRIM21 in myeloma cells." (PMID 32023548, 2020). "Protein arginine methyltransferases (PRMTs), particularly PRMT5 and PRMT1 identified in our study, are overexpressed in various cancers, including ovarian, lung, multiple myeloma, and breast tumors." (PMID 37684587, 2023). "In MM cell lines, treatment with a PRMT5 inhibitor decreases the levels of H4R3me2s at the CASP1 promoter, thus, enhancing the pyroptosis of myeloma cells." (PMID 36358861, 2022). "Another study reported that PRMT5 interaction with tripartite motif-containing protein 21 (TRIM21), an IKKβ ubiquitin ligase, inhibits IKKβ degradation in multiple myeloma, thereby inducing NF-κB signaling and cell growth of multiple myeloma cells." (PMID 34685445, 2021). "Finally, binding of PRMT5, MEP50, and pICln to Lsm10/11 heterodimers was observed in a mouse myeloma nuclear extract (lane 7), indicating that the interaction can occur in both the cytoplasmic and nuclear fractions from different mammalian cell lines." (PMID 37562960, 2023).